IL27 (interleukin 27)
Diseases named in the same sentence as IL27 in open-access papers (continued):
Sharing a sentence is not in itself a finding about the gene and the disease.
infection (continued). "We further show that IL-27 inhibits proinflammatory cytokine production in response to infection with M. tuberculosis, and subsequent mycobactericidal activity of macrophages." (PMID 36863206, 2023). "Further analysis showed that a 2‐dose treatment (days −1 and 2 post‐infection) was sufficient to observe the effect of IL‐27 neutralization, although the enhancing effect was reduced when compared with 4‐dose treatment (Fig EV1B)." (PMID 37855243, 2023). "These mice were euthanized at day 1 post-infection, a time that corresponds with peak IL-27 levels and a critical period for control of bacteria." (PMID 36891292, 2023). "Mice treated with anti‐IL‐27 mAb in the early phase of the infection had higher proportions of PB PbT‐II cells comparable to continuously treated mice; those treated during late phase did not." (PMID 37855243, 2023). "Of note, similar to TNF-α and IL-6, the quantity of IL-27 decreased when TLR-2 or TLR-4 were blocked prior to infection." (PMID 36863206, 2023). "Taken together, PbT‐II cells in anti‐IL‐27 mAb‐treated and IgG‐treated mice were comprised of clearly distinct subpopulations on day 28 of infection." (PMID 37855243, 2023). "Among PbT‐II subpopulations on day 28 after infection in anti‐IL‐27 mAb‐treated mice, KLRG1−CD127− cells were a minor population but exhibited the highest Tmem signature." (PMID 37855243, 2023). "Despite this lack of increase, the total number of PbT‐II cells remained higher in antimalarial‐treated anti‐IL‐27 mAb‐treated mice when compared with its IgG‐treated counterpart in both PB and spleen after 28 days of infection." (PMID 37855243, 2023). "In contrast to amniotic fluid, IFN‐β, IL‐10, IL‐6, and IL‐27 levels were undetectable in response to infection, and TNF‐α levels were decreased albeit barely above the limit of detection." (PMID 37259639, 2023). "A further functional maturation analysis of DCs revealed that IL-27 signaling restricted the protein and mRNA expression of IL-10 from DCs following infection." (PMID 36985179, 2023). "Mice infected with Pcc under IL‐27 neutralization condition were resistant against challenge infection with heterologous parasite, PbA." (PMID 37855243, 2023). "Twenty-four h after infection IL-10, LIF, M-CSF, IL-6, and IL-27 upregulation with the same mAbs was associated with protection in mice." (PMID 37289480, 2023). "The IL-27 concentration was quite high in control, uninfected MDMs (>70 pg/mL) and increased after infection by approximately 50% (106.5 pg/mL)." (PMID 37781389, 2023). "Nonetheless, we concomitantly detected a consistent upregulation of the IL27 gene throughout the infection." (PMID 37920474, 2023). "IL-27 is a pleiotropic cytokine involved in infection, cellular stress, neurological disease, and cancer that has complex activating and inhibitory properties in both innate and acquired immunity." (PMID 35743705, 2022). "S. aureus induced significant concentration-dependent IL-27 secretion 24 h post-infection in both RAW 264.7 macrophages and M0, M1, and M2 murine macrophages (P < 0.05)." (PMID 36028492, 2022). "Increased IL-10-producing T cells due to IL-27 was found to enhance survival during infection with viruses such as IAV, RSV, and SeV by attenuating immune cell infiltration, cytokine production, and inflammation." (PMID 35634328, 2022). "C57BL/6 (WT) and IL-27Rα−/− mice were challenged with bioluminescent MRSA (USA300 LAC::lux), and tibiae were harvested 14 days post-infection to assess the bacterial load and measure IL-27 levels via ELISA." (PMID 36028492, 2022). "To address this question, we treated MΦ with 100 ng recombinant IL-27 prior to infection with O. tsutsugamushi (5 MOI) and assessed key markers at 6 hpi." (PMID 36678402, 2022). "Surprisingly, murine calvarial MC3T3-E1 osteoblasts and primary bone marrow-derived osteoblasts produced significantly higher amounts of IL-27 at 24 h post-infection (P < 0.05)." (PMID 36028492, 2022).
infection (continued). "IL-27 mRNA was expressed at low levels at 30 days post-infection and at significantly higher levels at 60 days." (PMID 36189368, 2022). "IL-27 is a pleiotropic cytokine that regulates tissue reactions to infection, neuronal disease and tumors by inducing anti-apoptotic and anti-inflammatory genes and suppressing pro-inflammatory genes." (PMID 36064575, 2022). "Studies indicate that the initial production of IFN-γ following infection is maintained through IL-27." (PMID 34996392, 2022). "This is notable since our previous report utilizing single CLR-deficient (e.g., Mincle−/−) MΦs displayed nominal reductions in Tnf and Il27 transcripts early in infection (4 hpi)." (PMID 36678402, 2022). "Cytokines, including IL-27, are central for the timely induction of immune responses during infection." (PMID 36028492, 2022). "In the current study, we characterized the interactions among Ly6C+ monocytes, Ly6C− monocytes, and CD4+ T cells in the context of IL-27 signaling in a mouse model of infection with African trypanosomes." (PMID 33593983, 2021). "IL-27 prevents intrahepatic accumulation of Ly6C+ monocytes and their differentiation to moDCs and Tip-DCs upon infection." (PMID 33593983, 2021). "A previous study showed that liver damage during P. berghei NK65 induced infection was mediated by IL-27 in an IL-10 independent manner." (PMID 34906158, 2021). "In this study, we also found that the IL-27 expression is decreased in the liver when pretreated with GdCl3 in a CLP-induced severe infection mouse model." (PMID 33564275, 2021). "The serum and liver IL-27 expression levels were elevated in WT mice after CLP-induced severe infection, which were consistent with the changes in HE scores in the liver tissue." (PMID 33564275, 2021). "Together, this study provides the first evidence for a selective expression of Mincle in sensing O. tsutsugamushi and suggests a potential role of Mincle- and IL-27-related pathways in host responses to severe infection." (PMID 34320039, 2021). "IL-27 plays a remarkable role in the evolution of various diseases through its involvement in antitumor immunity and anti-infection immunity." (PMID 33954170, 2021). "Genome-wide expression analysis has indicated that IL-27 combined with PCT is a better predictor of infection than either biomarker alone." (PMID 33954170, 2021). "The differences in Il27 and Cxcl10 production in infected Mincle-/- and WT cells was even more pronounced by 24 hr post-infection." (PMID 34320039, 2021). "IL-27Rα−/− CD4 T cells were more glycolytic, suggesting that IL-27 seems to limit Th1 cell glycolysis to further protect against tissue pathology during infection." (PMID 34045653, 2021). "The identification of Il27 and other immunologic pathways that were significantly increased (Ccl2-5) or reduced (Ccrl1, Ahr) during infection have opened new avenues of investigating immune responses to O. tsutsugamushi." (PMID 34320039, 2021). "Infection with γHV-68 alone induced expression of multiple cytokines, including IL-27, IL-23, IL-12, IL-6, and IL-2, while stimulation with kyn alone failed to increase cytokine expression." (PMID 33491663, 2021). "More importantly, we found that such TNFα-mediated enhancement during infection was 2- to 3-folds reduced in Mincle-/- MΦs (Il27, Cxcl10, Ccl2), implying the mitigation of proinflammatory responses." (PMID 34320039, 2021). "IFN-γ is secreted by innate immune cells soon after infection and stimulates DC, upregulating proinflammatory factors such as IL-12, IL-27, and TNF-α." (PMID 34093711, 2021). "Our results demonstrate that MDSCs increase the expression of nitric oxide synthase (NOS)-2, ARG1 and IL-27 genes during an infection both in vivo and in vitro." (PMID 34208904, 2021). "At the onset of infection, IL-27 promotes immune reaction at the infection site by inducing myelopoiesis, Th1 differentiation and IFN-γ production." (PMID 34079555, 2021).
infection (continued). "IL-27 limits proliferative T cell responses during infections and in autoimmune conditions to limit tissue damage." (PMID 34079555, 2021). "Obviously, IL-27 inhibits Ly6C+ monocyte differentiation into Tip-DCs, preventing early mortality during infection with African trypanosomes." (PMID 33593983, 2021). "An increased IL-27 production by MDSCs during an infection would be predicted to compromise of a bacterial clearance and increase mortality." (PMID 34208904, 2021). "At later stages of infection, IL-27 suppresses inflammatory responses by immune cells to avoid multi-organ failure due to excessive or sustained inflammation with prolonged antigen presentation and/or cytokine storm." (PMID 34079555, 2021). "At 24 hr post-infection, we observed significant increases in WT production of Il27, Cxcl10, and Cxcl9, which were diminished in Mincle-/- cells." (PMID 34320039, 2021). "For this, MDSC isolated from HIV-infected individuals were infected with M tuberculosis and treated with neutralizing IL-27 or isotype matched control antibody; intracellular M tuberculosis replication was determined at day-3 post-infection." (PMID 33995365, 2021). "Peripheral tissue analysis revealed systemic IL-27 expression, while myeloid cell profiling identified Gr-1- and F4/80-expressing cells as the most abundant producers of IL-27 during infection." (PMID 31818960, 2020). "This is the first report to describe the impact of elevated early-life IL-27 on the host response in a neonatal infection model while also defining the cell and tissue sources of cytokine." (PMID 31818960, 2020). "Later in the infection at 24 h, IL-27 transcripts were more widely increased across different tissues." (PMID 31818960, 2020). "Critically, we discovered that IL-27 signalling limited glycolysis in Th1 cells during infection that in turn attenuated inflammation." (PMID 33049000, 2020). "In contrast, IL-1β, IFN-γ, IL-22, IL-10, IL-27 and IL-35 were present in lower levels in the lungs of these mice at all post-infection periods assessed." (PMID 32647342, 2020). "The expression of both IL-27R subunits, including WSX-1 and gp130, are upregulated mainly in the fourth week after infection, indicating that the expression of IL-27 and its receptor is induced during L. infantum infection." (PMID 32849534, 2020). "We identified IL-27 as an important regulator of glycolysis in Th1 cells that limited host tissue damage in the spleen following infection." (PMID 33049000, 2020). "To determine cell types that contribute to the rising IL-27 levels during infection, we profiled cells in the blood and spleens by immunofluorescent labeling and flow cytometry." (PMID 31818960, 2020). "The differences in infection outcome relative to IL-27 suggest a microbe and Th1- versus Th2-dependent mechanism of immunity, as well as a potential threshold of IL-27 production necessary to modulate proper immunity." (PMID 31818960, 2020). "Taken together, these results indicate that IL-27 signalling limits glycolysis in Th1 cells in vivo in order to protect tissue architecture against infection-induced inflammation." (PMID 33049000, 2020). "IL-27 gene expression was measured in the lungs, livers, spleens, kidneys, and brains of mice at 10 and 24 h following infection." (PMID 31818960, 2020). "Therefore, IL-27 may represent a new effector mechanism of immune suppression by MDSCs and these cells may be important contributors to the increased susceptibility to infection of the neonatal population." (PMID 32802395, 2020). "IL-27 s in BALFs from MP mixed infection group were significantly lower than those from MP single infection group and control (P < 0.05) respectively." (PMID 32393186, 2020). "Neutralization of IL-27 significantly improves survival of septic mice and clearance of P. aeruginosa, implying that it plays a pathophysiological role during infection." (PMID 33276561, 2020).
infection (continued). "While initial research established MDSCs as key regulators of tumor micro-environments and cancer progression, recent studies have begun to elucidate the role of MDSC-derived IL-27 in neonatal immunity during infection." (PMID 32802395, 2020). "At the same time, the infection and pathology of the Leishmania species are unique and vary with IL-27 dependency." (PMID 32849534, 2020). "Expression of IFNG, IL17A, IL12B, and IL27 was analyzed with PBMCs and PP cells isolated at 28 days post-infection and re-stimulated with individual recombinant MAP proteins." (PMID 33329565, 2020). "Since epithelial (and endothelial) barrier disruption acts as an initiator of a pro-inflammatory response during infection, Diegelmann and colleagues show that IL-27 has a role in limiting intestinal inflammation." (PMID 32802395, 2020). "We found IL-27 signalling was critical for the development of IL-10-producing Th1 (Tr1) cells during infection." (PMID 33049000, 2020). "In contrast to IL-23, IL-27 serum levels sharply increased after infection in wt and to a much lower extent in C5ar1−/− animals." (PMID 32733463, 2020). "We are the first to profile IL-27-producing cells in the blood and tissues during septic infection of any age group." (PMID 31818960, 2020). "The production of IL-27 led to enhanced bacterial survival in neutrophils which was reduced by blockade of neutrophil-derived IL-27 prior to infection." (PMID 32425944, 2020). "This was consistent with the presence of increasing numbers of CD11b+ and CD11c+ cells expressing IL-27 and programmed death-ligand 1 (PD-L1) markers although both plateaued at 50 days of infection related with T cell immune suppression." (PMID 31001241, 2019). "The data suggests a MAP driven immune response favouring the establishment of infection, as a strong induction of anti-inflammatory mediators such as IL-10, IL-27 and Suppressor of Cytokine Signalling (SOCS) 1 and 3 was observed." (PMID 30733564, 2019). "Among various Chains of IL-12 family, the expressions of IL-12 (p35) and EBI-3 were progressively elevated with infection, whereas, the expression of IL-27 (p28) chain was found unaltered." (PMID 31031744, 2019). "Studies on different subunit chains of IL-12 family revealed that p35 chain of IL-12 and EBI-3 were gradually up regulated, while p28 of IL-27 and p40 of IL-12 remained restricted during the course of infection." (PMID 31031744, 2019). "The exception was the effect on pDCs, which required IL-27 signaling to optimally maintain their numbers early after infection." (PMID 29593047, 2018). "To elucidate if IL-27 manipulated the cellular response to infection with bacteria, we infected IL-27 treated human macrophages with S. typhimurium." (PMID 30209294, 2018). "Since we observed an impact of IL-27 on the number of antiviral CD4 T cells present upon infection, we also normalized numbers of IFNγ producing CD4 T cells to the number of polyclonal CD11a+CD49d+ antiviral CD4 T cells detected." (PMID 30044874, 2018). "Cell death was monitored in PMA-THP-1 cells that were either cultured in medium (control) or pre-treated with IL-27 followed by stationary phase S. typhimurium (or mock) infection for 1.5, 8, or 12 hours." (PMID 30209294, 2018). "Infection with Mtb IL-27 was described to suppress T-cell responses by the reduction of TNF, IL-12p40, and IFN-γ expression and to inhibit T-cell recruitment and proliferation." (PMID 29541071, 2018). "When IL-27 was administered early in infection, it resulted in impaired viral clearance and worsened disease; however, when administered late in infection, there was decreased pathology, increased survival, and no impact on viral clearance." (PMID 29988424, 2018). "To our knowledge, IL-27 mediated restriction of a cytotoxic program in antiviral CD4 T cells has not been described before and we sought to identify the relevant cellular source for this new role of IL-27 during infection." (PMID 30044874, 2018).
infection (continued). "Narrowing the definition of infection yielded similar AUC’s for IL-27 but slightly improved AUC’s for PCT." (PMID 30475852, 2018). "IL-27 was enhanced rapidly by DCs and other myeloid cells upon infection, with pDCs in particular upregulating IL-27 transcripts in a TLR7-dependent fashion." (PMID 29593047, 2018). "Depletion of CD4+ T cells in IL-27Rα-/- mice led to a decrease in AAMs and reduced weight loss after infection, while eliminating STAT6 signaling in IL-27-deficient mice reduced Th2 responses and decreased mortality." (PMID 28129374, 2017). "The impact of IL-27 on the liver inflammation in both T. congolense and T. cruzi infections has been assessed." (PMID 29033934, 2017). "Several studies indicate that IL-27 has anti-inflammatory properties, which limit the severity of autoimmune disorders and regulate immunopathology during infections." (PMID 28255204, 2017). "We found that the levels of IL-1α, INF-γ, TNF-α, MCP-1, IL-1β, IL-10, IL-6, IL-27, and IL-17α in the lungs post infection were significantly different between alcohol- and pair-fed mice." (PMID 28604843, 2017). "Early depletion of IL-6 significantly reduced the concentration of IL-27 in the airways and lungs throughout infection." (PMID 28953978, 2017). "IL-6 is critical in enhancing the production of IL-27 by both resident and infiltrating myeloid cells after infection." (PMID 28953978, 2017). "We have found that the early production of IL-6 after infection promotes the production of the regulatory mediator Interleukin-27 by lung resident immune cells, which in turn drives suppression of otherwise damaging inflammation." (PMID 28953978, 2017). "There are multiple potential sources of endogenous IL-27, and while macrophages and DCs are considered major contributors, a more recent report suggested that during infection with Plasmodium berghei CD4+ T cells also produced IL-27." (PMID 28129374, 2017). "The resulting data revealed a relation between the levels of IL-27 and infection establishment, as the neutralization or the supply of IL-27 resulted in decreased or increased parasite burdens, respectively." (PMID 27867384, 2016). "IL-27 acted in the initial stages of infection to impinge on T cell responses and antiviral control." (PMID 27926930, 2016). "By eight weeks after infection, this anti-inflammatory response became more evident: IL-35, IL-27, and TGF-β appeared in reduced levels in contrast to the elevated concentrations of Th1 and Th17 cytokines in the lungs of pDC-depleted mice." (PMID 27992577, 2016). "We identified that IL-27, which was produced by myeloid cells during the initial days of infection, promoted the generation of IL-10+CD4+ T cells in the spleen." (PMID 27926930, 2016). "The present study clearly revealed that WSX-1/IL-27 contributes to clearance of parasites due to enhanced myelopoiesis during the early phase of infection with attenuated P. berghei XAT." (PMID 26991425, 2016). "Augmentation of L. amazonensis in cells was inhibitable by addition of anti-IL-27 to the infection cultures." (PMID 27148265, 2016). "Probably, the initial immune response of BALB/c is less inflammatory and less capable of limiting infection installation, suggesting again that the parasites directly induce the production of IL-27 for their own benefit." (PMID 27867384, 2016). "In mice, IL-27 appears to be essential to prevent severe immunopathology after infection with both cutaneous and visceral strains, mainly through the effects of IL-10." (PMID 27867384, 2016). "In children, the production levels of regulatory IL-27 and also of inflammatory IL-33 rose with the number of infections (G0 < G < G3+) and these responses were inducible by mite-allergen extracts." (PMID 25698903, 2015). "As recent studies have shown that IL-27 mainly regulates CD4+ T cell activation during infection with intracellular pathogens, we further evaluated IFN-γ-producing CD4+ T cells in the spleen cultures using flow cytometry." (PMID 26222157, 2015).